CD9 (CD9 molecule)
Description:
Integral membrane protein associated with integrins, which regulates different processes, such as sperm-egg fusion, platelet activation and aggregation, and cell adhesion. Present at the cell surface of oocytes and plays a key role in sperm-egg fusion, possibly by organizing multiprotein complexes and the morphology of the membrane required for the fusion (By similarity). In myoblasts, associates with CD81 and PTGFRN and inhibits myotube fusion during muscle regeneration (By similarity). In macrophages, associates with CD81 and beta-1 and beta-2 integrins, and prevents macrophage fusion into multinucleated giant cells specialized in ingesting complement-opsonized large particles. Also prevents the fusion between mononuclear cell progenitors into osteoclasts in charge of bone resorption (By similarity). Acts as a receptor for PSG17 (By similarity). Involved in platelet activation and aggregation. Regulates paranodal junction formation (By similarity). Involved in cell adhesion, cell motility and tumor metastasis.
Synonyms: MRP-1; Tspan-29; MIC3; TSPAN29; BA2; P24; BTCC-1; DRAP-27
Tractability: Small molecule: a structure with a bound ligand is known. Antibody: UniProt places it where antibodies can reach, with high confidence; its Gene Ontology location is reachable by antibodies, with high confidence; UniProt predicts a signal peptide or a membrane-spanning region; the Human Protein Atlas places it where antibodies can reach. PROTAC: ubiquitination databases record sites on it; its protein half-life has been measured.
Gene: Protein-coding gene on chromosome 12 (6,199,715 to 6,238,271, forward strand). Ensembl gene ENSG00000010278.
Subcellular location: Cell membrane; Membrane; Secreted, extracellular exosome
Subcellular location (Human Protein Atlas): Plasma membrane
Pathways (Reactome):
Disease: Uptake and function of diphtheria toxin
Hemostasis: Platelet degranulation
Reproduction: Acrosome Reaction and Sperm:Oocyte Membrane Binding
Gene Ontology:
Molecular function: integrin binding; protein binding
Biological process: cell adhesion; fusion of sperm to egg plasma membrane involved in single fertilization; glial cell migration; negative regulation of platelet aggregation; cellular response to low-density lipoprotein particle stimulus; myoblast fusion involved in skeletal muscle regeneration; paranodal junction assembly; platelet activation; receptor internalization; sperm-egg recognition; cell differentiation; nervous system development; oligodendrocyte development; regulation of macrophage migration; single fertilization
Cellular component: extracellular exosome; extracellular region; extracellular vesicle; focal adhesion; membrane; plasma membrane; protein-containing complex; clathrin-coated endocytic vesicle membrane; endocytic vesicle membrane; platelet alpha granule membrane; apical plasma membrane; cell surface; external side of plasma membrane
Genetic constraint (gnomAD): Loss-of-function variants: 4 observed, 16.49 expected, observed/expected ratio (o/e) 0.24, 90% interval 0.12 to 0.56. The upper end of that interval is the gene's LOEUF score, 0.56, which puts it in group 2 of 6, group 1 being the genes least tolerant of losing a copy. Missense variants: 168 observed, 183.69 expected, observed/expected ratio (o/e) 0.91, 90% interval 0.81 to 1.04. Synonymous variants: 69 observed, 73.84 expected, observed/expected ratio (o/e) 0.93, 90% interval 0.77 to 1.14.
Homologues: Orthologues: chimpanzee CD9 (99% identical), macaque CD9 (99% identical), dog CD9 (91% identical), rat Cd9 (91% identical), pig CD9 (90% identical), mouse Cd9 (89% identical), guinea pig CD9 (80% identical), tropical clawed frog cd9 (63% identical). Paralogues in human: TSPAN2 (46% identical), CD81 (45% identical), TSPAN8 (32% identical), CD151 (31% identical), TSPAN18 (29% identical), TSPAN9 (29% identical), TSPAN1 (28% identical), TSPAN5 (28% identical), TSPAN7 (28% identical), TSPAN11 (27% identical), CD82 (27% identical), TSPAN4 (26% identical), and 20 more.
Diseases named in the same sentence as CD9 in open-access papers:
CD9 is named in the same sentence as 274 diseases in open-access papers, as found by Europe PMC text mining. Sharing a sentence is not in itself a finding about the gene and the disease. The quoted sentences say what the papers report.
breast carcinoma (74 papers, 2009 to 2026). "In subgroup analysis of cancer type, an increased CD9 expression was associated with increased OS in breast cancer and digestive system cancer, and with increased DFS in head and neck cancer and leukemia/lymphoma." (PMID 34493282, 2021). "Low expression of CD63 and CD9 was associated with poor prognosis in patients with breast cancer, pancreatic cancer, and lung cancer." (PMID 34316329, 2021). "Decreased expression of CD63 and CD9 was associated with metastatic potential in patients with breast cancer, colon cancer, pancreatic cancer and Melanoma." (PMID 34316329, 2021). "CD9 is downregulated in vitro and in vivo in epithelial to mesenchymal transition, in which CD9 expression is associated with an epithelial phenotype and good prognosis in breast cancer patients." (PMID 32224917, 2020). "CD9 is also known as a marker of extracellular vesicles (EVs), and EVs are associated with breast cancer metastasis." (PMID 32640677, 2020). "This was expected, as the majority of the literature shows decreased CD9 expression in breast cancers, particularly associated with progression, and in lymph node metastases." (PMID 32224917, 2020). "Interestingly, CD9 was significantly co-localized with breast cancer-associated HPA-positive plasma-enriched sEVs compared to sEVs derived from healthy individuals compared to patients with non-metastatic cancer (p < 0.05)." (PMID 40411659, 2025). "Additionally, our results revealed that increased CD9 expression was associated with increased OS in breast cancer and digestive system cancer and with increased DFS in head and neck cancer and leukemia/lymphoma." (PMID 34493282, 2021). "In addition, the downregulation of CD9 is tightly associated with a poor prognosis in breast cancer, non-small-cell lung cancer, colon cancer and multiple myeloma." (PMID 24520284, 2014). "For example, CD9 is overexpressed in 10% of breast cancers and has been implicated in breast tumour invasion, yet CD9 is expressed in approximately 90% of all normal breast epithelial cells, highlighting that CD9 may mark diverse cell functions in the different epithelial cell lineages." (PMID 34120626, 2021). "The expression of CD9 in breast cancer is related to the epithelial phenotype and good prognosis of its patients." (PMID 40860827, 2025). "We isolated TDEs from E0771 breast cancer cell supernatant and validated their identity by CD9, CD63, and GAPDH expression, nanoparticle tracking analysis (NTA), and transmission electron microscopy (TEM)." (PMID 40695812, 2025). "Research across various cancers, including prostate cancer, lung cancer, colon cancer, breast cancer and mesothelioma, has demonstrated that CD9 can inhibit tumor growth and progression." (PMID 40860827, 2025). "Using counting beads for absolute quantification of events, we determined CD9+EVs to be present in concentrations ranging between 3 and 5 × 103 per μl in the supernatants of the different breast cancer cell lines." (PMID 40524202, 2025). "Using flow cytometry analysis to detect the exosome marker CD9, we found CD9-expressing EVs in all breast cancer cell lines investigated here." (PMID 40524202, 2025). "Given the potential diagnostic implications of HPA-positive sEVs and their co-localisation with CD9, further investigation of this interaction is warranted to explore its utility in enhancing breast cancer diagnosis." (PMID 40411659, 2025). "Another interesting finding was the observed increase in CD9 co-localisation in HPA-positive plasma-enriched sEVs derived from breast cancer patients compared to healthy individuals, though small, suggesting a potential avenue for diagnostic investigation." (PMID 40411659, 2025). "dSTORM imaging visualised single fluorochrome-labeled antibodies bound on individual EVs and revealed the expression of CD9 molecules on EVs derived from both breast cancer cells." (PMID 40524202, 2025).
breast carcinoma (continued). "Overexpression of CD9 was found in ovarian cancer compared to benign tissues and was found to promote the development of breast cancer bone metastasis." (PMID 40565320, 2025). "It was found that overexpression of CD9 can promote adhesion, migration and invasiveness in breast cancer cells." (PMID 40860827, 2025). "Western blot results showed that the exosome markers TSG101 and CD9 were expressed in exosomes derived from breast cancer cells." (PMID 39198393, 2024). "Decreased cell migration was also reported in highly metastatic hepatocellular carcinoma cells upon CD9 silencing or in breast cancer cells using CD9-binding peptide." (PMID 37007105, 2023). "Functionally it has been demonstrated that CD9 knock-down in extracellular vesicles from breast cancer cells or recipient cells reduced endocytosis." (PMID 37007105, 2023). "In breast cancer studies, CD9 also has been reported to be involved in tumor invasion and in inhibition of tumor progression that would be expected to have opposite effects on outcomes." (PMID 37542044, 2023). "Breast cancer plasma EVs displayed a unique proteome profile, with typical EV markers, such as CD9, CD81, CD63, and HSP70; Rab proteins; and clathrin." (PMID 37629204, 2023). "In our previous study, using melanoma or breast cancer cells, we showed that CD9 depletion in EVs also interfered with their cellular uptake, indicating that CD9 in both recipient cells and EVs is involved in this process." (PMID 36010551, 2022). "In summary, the surface protein profile of EVs from breast cancer patients suggested that EVs with the typical EV markers CD9, CD63 and CD81 were of cancer cell origin, as well as released by antigen-presenting cells and platelets." (PMID 35012489, 2022). "The expression of characteristic markers for exosomes and EVs varied, but all EV lysates from breast cancer lines were positive for CD9 and CD81, whilst the presence of CD63 was more variable." (PMID 35318648, 2022). "It does seem to hold the same properties, though, in breast cancer in regard to cell migration and proliferation as CD9 and CD63, and suppression of this surface protein is reported to reduce cancer invasion and metastasis." (PMID 36555738, 2022). "It has been shown that the presence of CD9 on the surface of EVs and/or on the plasma membrane of recipient breast cancer cells is essential for the uptake of EVs, as its silencing by RNA interference prevents internalization." (PMID 36010551, 2022). "TβRII is rather abundant and specifically enriched in EVs from metastatic breast cancer cells as its expression intensity even exceeds EV markers such as CD9 and CD81." (PMID 35915084, 2022). "In a similar context, an upregulation of CD81 was observed in breast cancer cells upon silencing CD9." (PMID 36010551, 2022). "On the contrary, other studies suggested that an increased CD9 expression was related to poor prognosis in patients with breast cancer and acute lymphoblastic leukemia." (PMID 34493282, 2021). "There are a few studies that have shown that CD9 knockdown in breast cancer cells leads to decreased motility and cell spreading." (PMID 32224917, 2020). "Treatment with an anti-CD9 antibody was shown to delay homing of osteotropic breast cancer cells in the bone marrow and therefore slow bone destruction in vivo." (PMID 32224917, 2020). "In contrast, there is evidence to suggest that CD9 knockdown in breast cancer cell lines leads to increased cell proliferation in 3D culture, which is not observed with standard 2D cell culture." (PMID 32224917, 2020). "ADAM-10 levels were significantly increased in subpopulations of CD9-positive exosomes isolated from the plasma and total blood fractions of patients with luminal breast cancer, as compared with HFs and triple-negative subtype BCPs." (PMID 32218180, 2020).
breast carcinoma (continued). "Breast cancer cell lines displayed lower CD9 mRNA, total protein, cell surface protein expression, and increased activity towards the CD9 3′UTR compared to non-tumorigenic breast cell lines." (PMID 32224917, 2020). "The subcellular co-localization of CLDN-1 and CD9 supports their interaction, and this was confirmed in many cell clines including different human breast cancer cell lines." (PMID 31952355, 2020). "Most in vitro studies concerning CD9 functions in breast cancer have focused on its modulation of motility/migration or epithelial to mesenchymal transition." (PMID 32224917, 2020). "Such that breast cancer metastases to the lungs, lymph nodes, and thoracic cavity can be controlled using human-specific anti-CD9 or anti-CD63 antibodies which target CD9/CD63 receptor on the surface of EVs." (PMID 32509768, 2020). "Knockdown of CD9 in breast cancer cells has been shown to increase motility, however, another study found delayed cell spreading and decreased motility often involving impaired integrin signaling." (PMID 32224917, 2020). "Given the important, albeit contrasting, role of CD9 in breast cancer progression to metastatic disease, this study also sought to determine the effect of Cd9 ablation on breast cancer initiation, growth, and progression to metastasis in vivo." (PMID 32224917, 2020). "Overexpression of CD9 has been found to be related to invasiveness and metastases in breast cancer cells." (PMID 32787954, 2020). "For example, patients with invasive luminal A subtype breast cancers had a poorer prognosis if they had high levels of CD9 in cancer cells, whereas patients with luminal B breast cancers had a good prognosis with CD9 protein expression in stromal cells." (PMID 32224917, 2020). "Whilst CD9 protein levels are commonly lower in breast cancers, which cells are expressing CD9 within tumors and which tumor sub-type is being assessed significantly affects the prognostic outcome of this." (PMID 32224917, 2020). "We observed that the majority of breast cancer cell lines had significantly lower CD9 mRNA, total protein, and cell surface protein levels compared to non-tumorigenic breast cells." (PMID 32224917, 2020). "CD9 has also been shown to play a role in cancer cell extravasation in vivo, and transient overexpression of CD9 on the cell surface of MDA-MB-231 breast cancer cells resulted in increased migration." (PMID 32224917, 2020). "Western blot analysis show that EpCAM-positive breast cancer exosomes express AnxA2 and exosomal markers CD9, TSG101, and flotillin-1." (PMID 31992335, 2020). "miR-518f-5p was overexpressed in breast cancer cell lines that displayed significantly lower CD9 expression as well as less endogenous CD9 3′UTR activity, as assessed using qPCR and dual luciferase assays." (PMID 32224917, 2020). "CD9/CD81 also regulate α3β1 integrin, loss of these two tetraspanins impairs breast cancer spreading, motility, and disrupts its association with PKCα in a CD151-independent manner." (PMID 29946318, 2018). "In breast cancer, the interaction of claudin 1 with CD9 has been shown to coincide with its subcellular co-localization in breast cancer." (PMID 26633531, 2015). "Here using paraffin-embedded immunohistochemistry of primary breast cancer specimen we found a network of BMHC (CD9+CD10+) surrounding cancer cell clusters." (PMID 26231656, 2015). "MDA-MB-231 breast carcinoma cells depleted of CD9 were reported to display enhanced proliferation in 3D Matrigel (over a 5 day period), and reduced spreading (but enhanced chemotactic migration) on fibronectin." (PMID 23613949, 2013). "To begin to clarify which aspects of α3β1 function require which tetraspanins, we created breast carcinoma cells depleted of both CD9 and CD81 by RNA interference." (PMID 23613949, 2013). "If PKCα does promote breast cancer metastasis through α3β1 integrin, our new data strongly suggest that the CD9/CD81 complex plays a key role." (PMID 23613949, 2013).
breast carcinoma (continued). "After preliminary experiments, in which silencing CD9 or CD81 alone in MDA-MB-231 breast cancer cells produced only modest phenotypic changes, we established cells with stable silencing of both tetraspanins (CD9/81si cells)." (PMID 23613949, 2013). "Specifically, HuR over-expression in ER- breast cancer (MB-231) paradoxically decreased CD9 mRNA and protein levels, whereas HuR knock-down increased the CD9 mRNA levels." (PMID 20370918, 2010). "HuR appears to differentially regulate the expression of CD9 in opposite directions in the two different forms of breast cancer." (PMID 20370918, 2010). "CD9 downregulation is a poor prognostic factor in many cancers, with CD9 expression inversely correlating with invasiveness in melanoma, breast carcinoma, squamous cell carcinoma, ovarian cancer, and cervical carcinoma." (PMID 19922654, 2009). "Moreover, since the five proteins CD9, CD24, CD63, CD81, and MMP9 are universal and present in exosomes secreted by both primary endotheliocytes and breast carcinoma cells, they cannot be part of the diagnostic panels being developed." (PMID 40310419, 2025). "Knockout of CD9 in breast cancer cells can increase cell motility, showing an anti-tumor effect." (PMID 40860827, 2025). "A similar observation was made in breast cancer cells upon silencing of CD9." (PMID 38243233, 2024). "Thus, it is possible that RNA and protein levels of CD9 do identify an ability to transition to a drug-resistant state at least in this subtype of breast cancer." (PMID 37542044, 2023). "The potential role of CD9 in metastasis was indicated in a different study, describing increased expression of CD9 in breast cancer bone metastasis compared to primary tumors, where CD9 antibody treatment in vivo moderately inhibited the progression of bone lesions." (PMID 37007105, 2023). "CD9 has been described as determining invasiveness and tumorigenicity in breast cancer cells." (PMID 36555738, 2022). "Similarly, CD9 overexpression is implied to play a role in breast cancer chemoresistance and is considered a biomarker for various cancers." (PMID 36555738, 2022). "The expression of ADAM10 on CD9-positive exosomes likely may be important in developing the luminal subtype of breast cancer." (PMID 33773551, 2021). "CD9, another tetraspanin, which was believed to be downregulated in most types of cancers, was demonstrated to promote cancer progression for prostate cancer, breast cancer, and osteosarcoma." (PMID 34830819, 2021). "Our study further identified a higher interaction frequency of CD9 promoter-distal looping in resistant breast cancer cells and illustrated that such higher expression is evidently associated with lower survival probability in endocrine-resistant breast cancer patients." (PMID 32787954, 2020). "Future work may focus on characterizing how chromatin looping of FN1 and CD9 functionally and mechanistically contributes to ERα + breast cancer resistant to the endocrine therapy." (PMID 32787954, 2020). "Moreover, the micro-RNA, miR-518f-5p was found to modulate CD9 expression and increase breast cancer cell migration in a panel of breast cell lines." (PMID 32224917, 2020). "While we have shown that miR-518f-5p may be responsible for the decrease in CD9 expression commonly observed in breast cancer progression, there is still a level of controversy in the literature as to the specific role of CD9 in breast cancer." (PMID 32224917, 2020). "Studies in breast cancer have shown that patients with high CD9 expression have significantly higher overall and relapse-free survival, and those with metastatic disease with high CD9 levels respond better to therapy." (PMID 32224917, 2020). "Moreover, CD9 is overexpressed in osteotropic breast cancer cells and bone metastases compared to primary tumors and visceral metastases." (PMID 32224917, 2020).